PFKFB3 (6-phosphofructo-2-kinase/fructose-2,6-biphosphatase 3)
Diseases named in the same sentence as PFKFB3 in open-access papers (continued):
Sharing a sentence is not in itself a finding about the gene and the disease.
glioblastoma (continued). "Glioblastoma neurospheres exposed to a hypoxic environment show a 10-fold increased expression of PFKFB3, as well as upregulation of LDHA, pyruvate dehydrogenase kinase 1 (PDK1), and HK-2, via HIF-1α signaling, particularly within the necrotic core." (PMID 34831136, 2021). "Motivated by these findings, we analyzed the PFKFB3-4 to PFKFB3-5 ratio in 30 IDH-wildtype glioblastomas and in 15 normal human brain samples." (PMID 34234350, 2021). "PFKFB3 mRNA is induced in hypoxia though a HIF-1α dependent mechanism in cancer cell lines from different tissues including glioblastoma, gastric and pancreatic cancer." (PMID 24280138, 2013). "PFKFB3, in particular the splice variant UBI2K4 is considered to be a tumor suppressor protein in glioblastomas." (PMID 24165198, 2013). "Another study shows that UBC9‐induced‐PFKFB3 SUMOylation competitively prevents PFKFB3 polyubiquitination to promote aerobic glycolysis and proliferation of glioblastoma cells, also highlighting the role of protein posttranslational modification in modulating PFKFB3 expression and glycolysis." (PMID 41292194, 2025). "Inhibition of RAS down-regulates HIF-1alpha and reduces PFKFB3 expression and might therefore block invasiveness, survival, and angiogenesis in Glioblastoma multiforme." (PMID 37253634, 2023). "Among glycolytic enzymes, PFKFB3 was the enzyme with the highest expression in glioblastoma." (PMID 34831136, 2021). "Similarly to glioblastoma cell lines, the ratio of PFKFB3-4 to PFKFB3-5 in IDH-wildtype glioblastomas was directed towards splice variant PFKFB3-4." (PMID 34234350, 2021). "This begs the question whether the ratio of PFKFB3-4 to PFKFB3-5 is relevant for neoplastic traits in glioblastomas." (PMID 34234350, 2021). "To gain more detailed insight about the role of PFKFB3-4 and PFKFB3-5 in glioblastomas, we employed the U87 glioblastoma cell line and investigated the knockdown and overexpression of these splice variants in relation to viability and proliferative capacity of U87 cells as a read out." (PMID 34234350, 2021). "LOH on 10p23-q24 has also been documented in glioblastomas causing loss of PTEN, resulting in reduced post-translational degradation of PFKFB3, and this may explain the overexpression seen even with chromosome 10 LOH." (PMID 34831136, 2021). "Hence, low PFKFB3-5 expression levels relative to PFKFB3-4 levels seem to confer growth advantage on glioblastomas." (PMID 34234350, 2021). "Glioblastomas with PFKFB3 LOH show reduced expression of the growth-inhibiting UBI2K4 variant, which may explain the downregulated expression and associated poor prognosis observed in some HGGs." (PMID 34831136, 2021). "Furthermore, we have shown that TGF-β1 overexpresses PFKFB3 mRNA and protein in glioblastoma cells through the activation of the Smad, p38 MAPK and PI3K/Akt signaling pathways." (PMID 30234009, 2018). "Moreover, TIGAR silencing has been shown to increase sensitivity of glioblastoma cells to radiotherapy and increase cell death mediated by PFKFB3 inhibition." (PMID 30234009, 2018). "For example, transforming growth factor-β (TGF-β1) induces PFKFB3 expression by activating the p38 MAPK and PI3K/Akt signalling pathways, thereby promoting glycolytic flux and lactate production in glioblastoma cells." (PMID 40307939, 2025). "High PFKFB3 LOH at 10p14-p15, as well as low UBI2K4 expression levels in glioblastoma, has been shown to portend a poor prognosis with an overall poor survival." (PMID 34831136, 2021). "Combined anti-PFKFB3 and anti-VEGF therapy has been noted to improve the survival of glioblastoma preclinical models and abrogate resistance to anti-angiogenic therapy." (PMID 34831136, 2021). "Inhibition of PFKFB3 as a method for TVN is thus a promising anti-tumorigenic treatment, as TVN has been shown to increase survival in glioblastoma patients." (PMID 34831136, 2021).
lung carcinoma (16 papers, 2016 to 2026). "NE significantly enhanced lung cancer cell proliferation, specifically upregulated PFKFB3 mRNA expression, promoted EMT marker (N-cadherin and Vimentin) expression, and increased cell migration capacity." (PMID 42157854, 2026). "This indicates that PFKFB3 functions as an oncogene-like regulatory element and that its elevated expression is an independent marker of overall survival in lung cancer patients." (PMID 41296396, 2025). "High expression of PFKFB3 in lung cancer plays a crucial role in regulating various cellular events including pathological angiogenesis, cell cycle progression, metastasis, and DNA repair." (PMID 41296396, 2025). "In lung cancer, the increased energy demands within cells result in a marked rise in the expression of PFKFB3, a regulatory protein involved in the glucose metabolic pathway." (PMID 41296396, 2025). "This binding activates PFKFB3's transcription, increases PFKFB3's expression and glycolysis, and encourages the growth and spread of lung cancer." (PMID 39661501, 2024). "Inhibition of PFKFB3 in a pre-clinical model of lung cancer reduced angiogenesis, decreased metastasis, enhanced barrier function, and improved drug delivery." (PMID 34061284, 2021). "Among these, PFKFB3 exhibits higher kinase activity and lower bisphosphatase activity compared with the other isoforms, leading to persistent activation of the PFKFB3 gene in lung cancer." (PMID 41296396, 2025). "In our previous work, we demonstrated for the first time that KAN0438757, a selective PFKFB3 inhibitor, exhibits potent anticancer activity by markedly reducing the survival and proliferation of A549 and H1299 lung cancer cells and suppressing colony formation and migration in A549 cells." (PMID 41296396, 2025). "Our findings imply that exploiting PFKFB3 as an autophagy flux mediator for therapeutic purposes could represent a novel combination treatment regimen against lung cancer tumors with intrinsic or acquired resistance to EGFR TKIs." (PMID 34359849, 2021). "Adding to the canonical understanding that PFKFB3 expression is essential to maintain elevated glycolytic flux in lung cancer cells to promote proliferation and survival, we provide evidence that PFKFB3 is required for erlotinib-induced cytoprotective autophagy." (PMID 34359849, 2021). "Fascin-1 was found to activate PFKFB3 transcription through the YAP1/TEAD binding site in its promoter to further promote glycolysis in NSCLC cells, thereby promoting lung cancer cell metabolism and growth." (PMID 36033434, 2022). "In lung cancer, FSCN1 promotes cancer growth and metastasis by enhancing glycolysis and PFKFB3 expression through YAP1 activation." (PMID 35069968, 2021). "The results in vitro and in vivo showed that G2, a pharmacological inhibitor of fascin-1, could significantly reduce the levels of PFKFB3 and YAP1 in lung cancer cells and nude mice." (PMID 36033434, 2022). "However, the role of PFKFB3 in regulating autophagy-dependent cell survival in lung cancer cells has not been established." (PMID 34359849, 2021).
atherosclerosis (15 papers, 2020 to 2025). A disease characterized by the build-up of fatty material and calcium deposition in the arterial wall resulting in partial or complete occlusion of the arterial lumen. "Altered endothelial metabolism is inextricably linked to atherosclerosis, especially PFKFB3 has been illustrated as a key regulator of glycolysis in ECs, and could therefore be a potential drug target." (PMID 34084561, 2021). "Targeting PFKFB3 has yielded promising results in the treatment of vascular-related diseases, such as cancer, pulmonary hypertension, and atherosclerosis." (PMID 38341583, 2024). "PFKFB3 also maintains endothelial cells in a quiescent state to reduce injury- and inflammation-induced pathological processes including atherosclerosis." (PMID 34336943, 2021). "The current study assessed the effect of partial myeloid Pfkfb3 disruption on atherosclerosis in vivo, after 12 weeks of HCD." (PMID 34458258, 2021). "A few studies have looked into partial pharmacological inhibition of glycolysis in atherosclerosis by targeting PFKFB3, using 3PO(-derivatives)." (PMID 34458258, 2021). "A recent study has shown that inhibition of PFKFB3 hampers the progression of atherosclerosis and promotes plaque stability mainly through decreased glycolysis in monocytes and macrophages." (PMID 34660743, 2021). "Higher levels of PFKFB3 have been detected in patients with symptomatic atherosclerosis and incident MI." (PMID 34336943, 2021). "Next to DCs and other myeloid cells, through analysis of scRNA-seq datasets, we showed that fibroblasts and SMCs, but also ECs and lymphocytes express PFKFB3/Pfkfb3 in human and murine atherosclerosis." (PMID 34458258, 2021). "This is accompanied by an increase in the incidence of intimal xanthomas (initial atherosclerotic lesions) upon PFK158 treatment, indicating that inhibition of PFKFB3 mitigates progression of atherosclerosis." (PMID 33282864, 2020). "In accordance with our findings, mRNA expression of glycolytic rate-limiting enzymes hexokinase 2 (HK2) and PFKFB3 is significantly elevated in monocytes isolated from patients with symptomatic atherosclerosis." (PMID 32350546, 2020). "PFKFB3 expression positively correlates with necrotic core area, indicating that PFKFB3 expression increases during the progression of atherosclerosis." (PMID 33282864, 2020). "In the present study, we analyzed the expression of PFKFB3 in human atherosclerotic lesions and explored the therapeutic potential of pharmacological inhibition of PFKFB3 in experimental atherosclerosis." (PMID 33282864, 2020). "Here, we analyzed the expression of PFKFB3 in human atherosclerotic lesions and investigated the therapeutic potential of pharmacological inhibition of PFKFB3 in experimental atherosclerosis by using the glycolytic inhibitor PFK158." (PMID 33282864, 2020). "Furthermore, as a key regulator of glycolysis, PFKFB3 has been regarded as a promising target for the treatment of multiple tumors, rheumatoid arthritis, pulmonary arterial hypertension, and atherosclerosis." (PMID 36405760, 2022). "In addition, it was also reported that inhibition of PFKFB3 improved the status of some benign diseases, such as rheumatoid arthritis and atherosclerosis." (PMID 36405760, 2022). "This confirms PFKFB3 expression in human atherosclerosis, and particularly in macrophages." (PMID 34458258, 2021). "After confirming partial Pfkfb3 knockdown, functional disruption of glycolysis and a decreased pro-inflammatory profile in macrophages in vitro, we studied the effects of myeloid Pfkfb3 disruption on atherosclerosis." (PMID 34458258, 2021).
atherosclerosis (continued). "In the context of atherosclerosis, it is important to note that in advanced human carotid plaques PFKFB3 expression was positively correlated with necrotic core area, indicating increased plaque vulnerability, whereas PFKFB3 was lower in the stable plaques having a thick fibrous cap." (PMID 34084561, 2021). "Instead, other Pfkfb3-expressing cells in atherosclerosis might be responsible, such as DCs, smooth muscle cells or fibroblasts." (PMID 34458258, 2021). "In line, human coronary atherosclerotic plaques, histologically classified as fibrous cap atheromata (advanced atherosclerosis) express higher levels of PFKFB3+ cells when compared with intimal xanthomas or pathological intimal thickenings (initial/intermediate atherosclerosis)." (PMID 33282864, 2020). "The role of PFKFB3 in disease mechanisms is perhaps best characterized by the development of cancer, but increasing evidence supports the important roles of PFKFB3 in major vascular diseases, such as atherosclerosis, pulmonary hypertension, diabetic retinopathy, and angiogenesis." (PMID 40002359, 2025). "Moreover, PFKFB3 has been shown to act as a therapeutic target and participate in a variety of regulatory mechanisms in various diseases, such as cancer, pulmonary hypertension, pulmonary fibrosis, and atherosclerosis." (PMID 38341583, 2024). "In addition to greater relevance of PFKFB3-mediated glycolysis in other cell types in atherosclerosis, or off-target effects of reported inhibitors, other factors may explain the observed lack of effect of myeloid Pfkfb3 inhibition on atherosclerosis." (PMID 34458258, 2021). "These overlapping influences converge on shared molecular nodes such as PFKFB3, eNOS, ADMA, ROS, and BH4/BH2, whose dysregulation reflects and reinforces vascular aging and atherosclerosis." (PMID 40890841, 2025). "In addition, PFKFB3 promotes ECs inflammation via tumor necrosis factor-α(TNF-α), which promotes the development of atherosclerosis." (PMID 41149255, 2025). "Except for myeloid-specific Pfkfb3 knockdown in the current study, effects of other cell-specific Pfkfb3 knockdowns in atherosclerosis have not been studied yet." (PMID 34458258, 2021). "Partial myeloid knockdown of PFKFB3 did not affect atherosclerosis development in advanced or early lesions." (PMID 34458258, 2021). "Collectively, our findings suggest that although myeloid Pfkfb3 disruption decreases the pro-inflammatory macrophage profile in vitro, it does not affect atherosclerosis development in vivo, neither in advanced, nor early lesions." (PMID 34458258, 2021). "In conclusion, we showed that partial myeloid knockdown of PFKFB3 does not affect atherosclerosis development." (PMID 34458258, 2021). "Targeting metabolic checkpoints—such as PFKFB3, PKM2, miR-33, or lactate-related pathways—may restore metabolic balance, suppress M1 polarization, and promote plaque stability, offering promising therapeutic strategies for atherosclerosis." (PMID 41149255, 2025). "However, while acute, systemic silencing of PFKFB3 ameliorated macrophage inflammation and atherosclerosis, chronic myeloid-specific inhibition of PFKFB3 did not have any effects on atherosclerosis." (PMID 39188527, 2024). "For example, IL18R1 was enriched in the TNF signaling pathway and cytokine–cytokine receptor interaction; PFKFB3 was enriched in fructose and mannose metabolism and HIF-1 signaling pathway; IL1R2 was enriched in hematopoietic cell lineage and fluid shear stress and atherosclerosis." (PMID 34336943, 2021). "Small molecule AZ67 does bind to PFKFB3 specifically and might be an interesting pharmacological inhibitor for future in vivo atherosclerosis studies, while keeping in mind that effects are likely not mediated by monocytes, macrophages or neutrophils." (PMID 34458258, 2021).
atherosclerosis (continued). "Notably, this network integrates key glycolytic regulators like PFKFB3 and lactate transporters like MCT1 with established inflammatory and signaling pathways, providing a computational framework and promising targets for future mechanistic and therapeutic research in atherosclerosis." (PMID 41149255, 2025). "Another factor that might explain the lack of effect on atherosclerosis compared to studies utilizing 3PO treatment, is recent evidence that 3PO inhibits glycolysis through intracellular acidification, rather than specific PFKFB3 inhibition." (PMID 34458258, 2021).
ovarian carcinoma (15 papers, 2015 to 2025). A malignant neoplasm originating from the surface ovarian epithelium. "In the present study, we demonstrate for the first time to the best of our knowledge that PFKFB3 is preferentially expressed in metastatic foci and ascites in ovarian cancer, suggesting that PFKFB3 could be associated with metastasis in ovarian cancer." (PMID 35155224, 2022). "PFKFB3 was further detected to be up-regulated in ascites-derived tumor cells compared with primary tumor cells by qPCR; thus, suggesting that PFKFB3 is associated with metastasis in ovarian cancer." (PMID 35155224, 2022). "Another study on PFKFB3 in ovarian cancer found that PFKFB3 promotes ovarian cancer metastasis by suppressing the NLRP3 axis, reducing pyroptosis, and enhancing the Warburg effect." (PMID 40718836, 2025). "CD99 and PFKFB3 have been previously found to mediate metabolic reprogramming, chemoresistance, metastasis, and stemness in ovarian cancer, likely via the modulation of inhibitors of apoptotic proteins and the NF-κB signaling pathway." (PMID 38339304, 2024). "Previous study indicated that PFKFB3 regulate both of proliferation and migration of ovarian cancer by regulating cytosolic protein tyrosine kinase 2 (focal adhesion kinase)." (PMID 37919747, 2023). "We found through IHC analysis that PFKFB3 was markedly higher in ovarian cancer tissues than normal ovary tissues, a finding consistent with Oncomine analysis results." (PMID 35155224, 2022). "miR-206 directly decreased the expression of glycolytic enhancer 6-phosphofructo-2-kinase/fructose-2,6-biphosphatase 3 (PFKFB3) and suppressed the proliferation of ovarian cancer cells." (PMID 36076996, 2022). "Detailed information about the 3 public expression datasets of Oncomine database about PFKFB3 in ovarian cancer." (PMID 35155224, 2022). "Higher PFKFB3 was associated with poorer overall (p=0.04) and progression-free (p=0.0035) survival; thus, suggesting a correlation between PFKFB3 and poor outcomes in ovarian cancer." (PMID 35155224, 2022). "Our in vitro and in vivo results show that PFKFB3 was overexpressed in ovarian cancer, ascites-derived tumor cells and CSC-enriched subpopulations." (PMID 35155224, 2022). "To study the effect of PFKFB3 on chemoresistance of ovarian cancer, we first detected PFKFB3 expression in A2780S and A2780CP cells after cisplatin treatment (0, 2.5, 5 and 10 μM) for 48 h." (PMID 35155224, 2022). "In conclusion, we demonstrated that overexpression of PFKFB3 in ovarian cancer cells, especially in the CSC subpopulation, correlates with metastasis and patient survival." (PMID 35155224, 2022). "We demonstrate that PFKFB3 is widely overexpressed in ovarian cancer and correlates with advanced stage/grade and poor outcomes." (PMID 35155224, 2022). "Statistical up-regulation of PFKFB3 was observed in ovarian cancer tissues compared with normal ovary tissues." (PMID 35155224, 2022). "To investigate the prognostic value of PFKFB3 in ovarian cancer at the mRNA level, we analyzed a clinical database (GSE26193) containing data from 107 patients, by using Kaplan-Meier Plotter with the auto-selected best cutoff." (PMID 35155224, 2022). "Overexpression of PFKFB3 in ovarian cancer correlates with metastasis and poor prognosis to study the role of PFKFB3 in ovarian cancer, we analyzed two independent microarray databases from Oncomine." (PMID 35155224, 2022). "A significant albeit very weak correlation was detected between high expression of PFKFB3 and upregulation of KLF4 and BMI1, suggesting KLF4 and BMI1 as the potential downstream targets of PFKFB3 on CSC properties in ovarian cancer." (PMID 35155224, 2022). "We investigate the clinical significance and roles of PFKFB3 in ovarian cancer using in vitro and in vivo experiments." (PMID 35155224, 2022). "We then investigated the effects and mechanism of PFKFB3 on ovarian cancer metabolic switch and regulation of chemoresistance to cisplatin using one of its inhibitors 3PO." (PMID 35155224, 2022).